SPATA20 (spermatogenesis associated 20)
Description:
May play a role in fertility regulation.
Synonyms: Ssp411; FLJ21347; Tisp78; HEL-S-98
Tractability: Antibody: UniProt places it where antibodies can reach, with high confidence; UniProt predicts a signal peptide or a membrane-spanning region; its Gene Ontology location is reachable by antibodies, with medium confidence. PROTAC: its protein half-life has been measured.
Gene: Protein-coding gene on chromosome 17 (50,543,058 to 50,556,481, forward strand). Ensembl gene ENSG00000006282.
Subcellular location: Secreted
Subcellular location (Human Protein Atlas): Principal piece; Predicted to be secreted
Gene Ontology:
Biological process: carbohydrate metabolic process
Cellular component: mitochondrion; extracellular region
Genetic constraint (gnomAD): Loss-of-function variants: 73 observed, 100.52 expected, observed/expected ratio (o/e) 0.73, 90% interval 0.6 to 0.88. The upper end of that interval is the gene's LOEUF score, 0.88, which puts it in group 3 of 6, group 1 being the genes least tolerant of losing a copy. Missense variants: 1,006 observed, 1,070.5 expected, observed/expected ratio (o/e) 0.94, 90% interval 0.89 to 0.99. Synonymous variants: 427 observed, 440.97 expected, observed/expected ratio (o/e) 0.97, 90% interval 0.89 to 1.05.
Homologues: Orthologues: chimpanzee SPATA20 (99% identical), macaque SPATA20 (99% identical), dog SPATA20 (92% identical), rabbit SPATA20 (92% identical), pig SPATA20 (90% identical), rat Spata20 (85% identical), mouse Spata20 (84% identical), guinea pig SPATA20 (84% identical), zebrafish spata20 (56% identical), tropical clawed frog spata20 (56% identical), Drosophila melanogaster CG8613 (40% identical), Caenorhabditis elegans B0495.5 (36% identical).
Diseases named in the same sentence as SPATA20 in open-access papers:
SPATA20 is named in the same sentence as 19 diseases in open-access papers, as found by Europe PMC text mining. Sharing a sentence is not in itself a finding about the gene and the disease. The quoted sentences say what the papers report.
ischemic stroke (2 papers, 2025 to 2026). A stroke disorder caused by obstruction of blood flow to the brain, due to thrombotic (local blood clot formation) or embolic (due to a blood clot or other material traveling from another site) event. "In conclusion, we found causal evidence supporting three classic genes MMP12, F11 and SCARA5, and three novel genes SH3BGRL3, SWAP70 and SPATA20 were associated with the risk of ischemic stroke and their subtypes." (PMID 41488603, 2026). "We found that fat mass independently increased plasma levels of all protein mediators (COL6A3-derived endotrophin, F11, PCSK9, C1R and SPATA20) and increased the odds of type 2 diabetes, CAD and ischemic stroke." (PMID 39856218, 2025).
male infertility (2 papers, 2022 to 2023). The inability of the male to effect fertilization of an ovum after a specified period of unprotected intercourse. "The presence of a null pathogenic variant in SPATA20 gene impairs the expression of both SPATA20 and SPATA6, leading to male infertility related to acephalic spermatozoa syndrome." (PMID 36833310, 2023).
Obesity (2 papers, 2020 to 2025). Accumulation of substantial excess body fat. "Lastly, SPATA-20, thioredoxin-like protein was investigated as an important protein upregulated in testicular oxidative stress (associated with HF diet and obesity) with increase in SPATA-20 noted thus validating LC-MS proteomic findings." (PMID 32678325, 2020). "SPATA-20 may have a protective role in sperm likely in the context of sperm oxidative stress which is well associated obesity." (PMID 32678325, 2020).
type 1 diabetes (2 papers, 2020 to 2025). "SPATA-20 expression is increased 5-fold in spermatogenic cells from patients with type 1 diabetes, where a deregulation of oxidative genes is noted when compared to healthy controls." (PMID 32678325, 2020).
type 2 diabetes (2 papers, 2025 to 2026). "We identified nine protein–disease associations after MR, sensitivity analyses and colocalization; these included associations of COL6A3 and PCSK9 with CAD, F11 with ischemic and cardioembolic stroke, and SPATA20 with type 2 diabetes." (PMID 39856218, 2025). "The effect of F11, SH3BGRL3, SPATA20 and SWAP70 on each subtype was mediated by Factor XI inhibitors, atrial fibrillation, type 2 diabetes and systolic blood pressure, respectively (P < 0.05)." (PMID 41488603, 2026).
Stroke (1 paper, 2026). Sudden impairment of blood flow to a part of the brain due to occlusion or rupture of an artery to the brain. "This analysis was restricted to four genes, F11, SWAP70, SH3BGRL3 and SPATA20, which showed evidence of an effect in both MRs with risk factors and stroke outcomes." (PMID 41488603, 2026). "We found that the protein abundance of seven genes (MMP12, F11, SH3BGRL3, ENGASE, SCARA5, SWAP70 and SPATA20) in the plasma was associated with stroke and its subtypes, and six genes (MMP12, F11, SH3BGRL3, SCARA5, SWAP70 and SPATA20) causally related with stroke and its subtypes." (PMID 41488603, 2026). "We identified 7 potential risk genes (MMP12, F11, SH3BGRL3, ENGASE, SCARA5, SWAP70 and SPATA20) of stroke with altered protein abundances in the plasma." (PMID 41488603, 2026). "The PWAS identified 7 genes (MMP12, F11, ENGASE, SH3BGRL3, SPATA20, SWAP70, SCARA5) whose cis-regulated plasma protein levels were associated with stroke and its subtypes at a FDR of P < 0.05." (PMID 41488603, 2026). "Interestingly, two genes identified in TWAS (SWAP70 and SPATA20) were also significant in the AIS and SVS PWAS, respectively, suggesting joint evidence from PWAS and TWAS for its role in stroke etiology." (PMID 41488603, 2026).
Tinnitus (1 paper, 2024). Tinnitus is an auditory perception that can be described as the experience of sound, in the ear or in the head, in the absence of external acoustic stimulation. "The most downregulated genes in the tinnitus (when compared to the non-tinnitus group) were LOC103690064, AABR07048397.1, Trpv1, AABR07061378.1, Ncaph, Spata20, Rps19, Enpp3, Grtp1, and Glra1." (PMID 38562529, 2024).
SPATA20 also shares sentences with these, for which no sentence is quoted: acephalic spermatozoa syndrome (1 paper); atrial fibrillation (1); cancer (1); cardioembolic stroke (1); cholangiocarcinoma (1); cholangitis (1); Globozoospermia (1); hilar cholangiocarcinoma (1); infertile (1); intrahepatic cholangiocarcinoma (1); lymph node metastasis (1); tumor (1).